THBS1 (thrombospondin 1)
Diseases named in the same sentence as THBS1 in open-access papers (continued):
Sharing a sentence is not in itself a finding about the gene and the disease.
melanoma (continued). "Ibuprofen, an activator of PPARα, was found to increase expression of CD36, the anti-angiogenic Thrombospondin-1 (TSP-1) receptor in human melanoma cells." (PMID 32785018, 2020). "Downregulation and enhanced silencing of THBS1 expression was also described as a consequence of DNA methylation in melanoma." (PMID 30197759, 2018). "The expression levels of the identified target genes encoding CTGF, THBS1, STMN1, BCL9, RAC1 and MCL1 allowed discrimination between phenotypic groups of melanoma cell lines with high or low-invasive capacity, respectively." (PMID 30197759, 2018). "For example, Thrombospondin 1 was reported to promote an aggressive phenotype through inducing EMT in melanoma." (PMID 27852070, 2017). "The role of THBS1 in melanoma cell invasion was evaluated using mesenchymal- and epithelial-like melanoma cells in matrigel based transwell invasion assays." (PMID 25051363, 2014). "We confirmed significant up-regulation of THBS1 by qRT-PCR performed on Dilbright cells derived from four melanoma cell lines on the array." (PMID 25051363, 2014). "This study therefore aimed to reveal the functional roles of THBS1 during melanoma progression by assessing THBS1 expression and its effects on the functional characteristics of melanoma cells, particularly those associated with mesenchymal transformation." (PMID 25051363, 2014). "Although we have clearly demonstrated that THBS1 mediates enhanced melanoma invasion in vitro and in vivo, previous studies that evaluated the role of THBS1 in cancer cell invasion have yielded mixed results." (PMID 25051363, 2014). "We propose that THBS1 promotes EMT in melanoma through activation of latent TGF-beta 1 during the progression of melanoma." (PMID 25051363, 2014). "Melanoma cells were transfected with siRNA targeting THBS1, cultured as a hanging drop for 24 hours and introduced into the trunk neural tube of a developing chick embryo." (PMID 25051363, 2014). "To better evaluate role of THBS1 in human melanoma, we determined its expression in metastatic melanoma tumor biopsies." (PMID 25051363, 2014). "Elevated THBS1 levels were detected in Vemurafenib resistant melanoma cells and inhibition of THBS1 led to significantly reduced chemoresistance in melanoma cells." (PMID 25051363, 2014). "The interplay between these molecules supports a role for positive feedback within the tumor and extends the observations of others that TGF-beta 1 induces EMT in melanoma and that THBS1 is a TGF-beta 1 activator." (PMID 25051363, 2014). "A recent study showed that the transcription factor SNAIL induces EMT in melanoma and leads to an increase in THBS1 expression and results in immunosuppression and enhanced metastasis." (PMID 25051363, 2014). "We compared gene expression signatures of mesenchymal-like melanoma cells with those of epithelial-like melanoma cells, and identified Thrombospondin 1 (THBS1) as highly up-regulated in the mesenchymal phenotype." (PMID 25051363, 2014). "qRT-PCR showed induction of THBS1 expression in melanoma cells treated with cytotoxic chemotherapy agents, such as taxol, cisplatin and 5-flurouracil after 72 hours." (PMID 25051363, 2014). "We assessed THBS1 function in an in vivo model of melanoma cell plasticity and invasion, the chick embryo." (PMID 25051363, 2014). "Analysis of the cutaneous melanoma dataset consisting of 376 melanoma patients available from TCGA revealed an increase in mRNA expression of THBS1 in 3% of patients." (PMID 25051363, 2014). "Here we show that THBS1 expression and secretion was elevated in melanoma cells exhibiting invasive, drug resistant, label retaining and mesenchymal phenotypes and correlated with reduced expression of genes involved in pigmentation." (PMID 25051363, 2014). "Whereas the role of THBS1 in angiogenesis in melanoma is well documented, its role in tumor metastasis is only just emerging." (PMID 25051363, 2014).
melanoma (continued). "THBS1 protein expression patterns in melanoma tumors were determined by immunohistochemical staining of a tissue microarrays (TMA) comprising of tumors from 103 patients with stage III and IV metastatic melanoma." (PMID 25051363, 2014). "The mechanism whereby THBS1 promotes melanoma invasion remains poorly understood, however we demonstrate that this is likely linked to TGF-beta activation." (PMID 25051363, 2014). "In melanoma cell lines, exposure to a demethylating agent reversed THBS1 promoter hypermethylation, increased THBS1 expression, and reduced angiogenesis in vivo." (PMID 24195060, 2013). "THBS1 promoter methylation levels were 3.5 and 2 times higher in melanoma cell lines and tumors respectively." (PMID 22028813, 2011). "Of these, the mRNA expression of THBS1 and THBS2 has been inversely associated with melanoma growth and progression, while CX3CL1 inhibition has been shown to reduce melanoma growth and angiogenesis in mice." (PMID 21615965, 2011). "Moreover, melanoma cell spreading and adhesion are promoted by the cooperation between αvβ3 integrin and the TSR1s domain of THBS1." (PMID 38339060, 2024). "Similarly, PTEN, NF1, KLF6, and THBS1 genes were frequently reported in different cancer gene resources as melanoma tumor suppressors." (PMID 37904237, 2023). "It has also been demonstrated that MSCs expressing thrombospondin-1 (TSP-1) in a metastasis melanoma model decrease nodule apparition and exerted an anti-tumor effect via an activation of T cells, an upregulation of Bax pro-apoptotic protein, and a downregulation of Bcl-2 anti-apoptotic protein." (PMID 37686315, 2023). "We also identified biomarkers, namely, ITGB1, FBN1, and THBS1, secreted by BC cells constituting lesions of all grades as well as the examined adenocarcinomas (colorectal, gastric, hepatocellular, melanoma, non-small cell lung cancer, ovarian, pancreatic, and prostate cancer)." (PMID 36010848, 2022). "THBS1 is overexpressed in the invasive phenotypes of melanoma and invasive ductal breast cancer." (PMID 34804159, 2021). "Therefore, we can draw a clear conclusion that THBS1 promotes the invasion and metastasis of melanoma, which is expected to become a target for future treatment." (PMID 32894090, 2020). "In addition, the data indicated that miR-205-5p expression negatively correlated with THBS1 in 449 skin melanoma samples, and that miR-205 affects the proliferation and metastasis of melanoma cells by targeting CCL18." (PMID 33186919, 2020). "As the main physiological activator of transforming growth factor-β (TGF-β), THBS1 may activate the latent TGF-β1 in the progress of melanoma to promote EMT of melanoma." (PMID 32894090, 2020). "In contrast to wild-type tumors with no thrombospondin-1 expression, a tumor-suppressive index was demonstrated only in mice bearing D-12, U-25, or thrombospondin-1 overexpressing R-18 tumors, as validated by melanoma angiogenesis, lung colonization, and spontaneous pulmonary metastasis." (PMID 31430951, 2019). "Also, eradication of primary tumors which result in inducing dormant tumor cells is evidenced by the high expression level of angiogenic inhibitor thrombospondin-1 in human melanoma xenografts (D-12, R-18, and U-25)." (PMID 31430951, 2019). "At two of these genes, THBS1 and TNFRSF10D, we identified a positive association between total body nevus count and promoter CpG methylation, in line with their findings of increased DNA methylation in advanced stage melanoma." (PMID 27993549, 2017). "THBS1 expression was also increased in label-retaining melanoma cell sub-populations." (PMID 25051363, 2014). "THBS1 can be epigenetically silenced in melanomas, marking it as a potential tumor-suppressor gene." (PMID 25051363, 2014).
melanoma (continued). "As a central player in these processes, THBS1 well may serve as a target in strategies to better treat malignant melanoma." (PMID 25051363, 2014). "Notably, siRNA-mediated silencing of THBS1 and neutralizing antibody to THBS1 reduced invasion in mesenchymal-like melanoma cells, while ectopic THBS1 expression in epithelial-like melanoma cells enhanced invasion." (PMID 25051363, 2014). "Similarly, we demonstrated that in vivo THBS1 knockdown abrogates the invasive/plastic potential of melanoma cells within the chicken neural tube." (PMID 25051363, 2014). "THBS1 could accelerate malignant cancer cell invasion in PCa and promote melanoma metastasis." (PMID 37730847, 2023). "SETDB1 has been found to be highly amplified in tumors of melanoma patients and melanoma cell lines, with overexpression contributing to a more aggressive phenotype in vivo and in vitro studies by upregulating thrombospondin 1 (THBS1) expression in a H3K4me1-dependent manner." (PMID 38057834, 2023). "However, a role of THBS1 in mediating EMT in melanoma remains to be elucidated." (PMID 25051363, 2014). "A central role is attributed to the angiogenesis inhibitor thrombospondin-1 (TSP-1), which is secreted by immune cells or melanoma cells in a xenograft model." (PMID 38419052, 2024). "Some of these include Dead H box helicase 11 (DDX11), Claudin 5 (CLDN5), chemokine CXC motif (CXCL1 ligand 1, melanoma growth), glutathione S-transferase mu 1 (GSTM1), major histocompatibility complex class I K (HLA-K), and thrombospondin 1 (THBS1)." (PMID 36769056, 2023). "For example, it is considered a major physiological activator of TGF-β1, and THBS1 promotes the EMT process in various cell types, including melanoma and oral squamous cell carcinoma, by activating TGF-β1." (PMID 37783703, 2023). "Murine and human melanoma cells with typical EMT features after SNAIL transduction induced regulatory T cells and impaired dendritic cells partly through thrombospondin-1 (TSP1) production." (PMID 34943943, 2021). "When the EMT TF Snail was overexpressed in B16F10 mouse melanoma cells, CD4+FoxP3+ Tregs were generated via MHCIIlo IDO-expressing regulatory DCs that developed in response to tumor production of thrombospondin-1 (TSP1)." (PMID 31921140, 2019). "We confirm previous reports that COL1A2, THBS1, TNFRSF10D and UCHL1 are highly methylated in melanoma, thus providing further evidence that these genes are highly important in melanocytic neoplasia." (PMID 22028813, 2011). "Some of these genes had already been described in earlier studies as being down-regulated during melanoma progression: COL17A1, DSC3, KLK7, SLPI and KLK8, or over-expressed, e.g. CCL20, THBS1 and THBS4." (PMID 22032772, 2011). "Summary of COL1A2, THBS1, TNFRSF10D and UCHL1 methylation in melanocytes, melanoma cell lines, fresh-frozen melanoma tumors and other cancer cell lines." (PMID 22028813, 2011). "The tumorigenic effects of SETDB1 are attributed to the regulation of Thrombospondin 1 (THBS1), which promotes melanoma invasiveness and metastasis as well as downregulation of the expression of DOPAchrome tautomerase (DCT), an enzyme that participates in melanin synthesis." (PMID 34440561, 2021). "Similarly, YAP overexpression stimulates spontaneous metastasis in experimental melanomas, while the silencing of YAP targets as AXL, THBS1 (Thrombospondin 1), and CYR61 represses metastasis." (PMID 34439395, 2021). "In this study, we highlighted the potential role of CXCL8, THBS1 and KIT in melanoma metastasis." (PMID 32894090, 2020). "To conclude, CXCL8, THBS1 and KIT may be the hub genes in the metastasis of melanoma and thus may be regarded as therapeutic targets in the future." (PMID 32894090, 2020).
melanoma (continued). "This study investigated whether THBS1, a major physiological activator of transforming growth factor (TGF)-beta, is involved in melanoma EMT-like process." (PMID 25051363, 2014). "As THBS1 is a known activator of TGF-beta and TGF-beta has a pivotal function in the progression of EMT, we examined the level of TGF-beta secretion in a subset of high and low THBS1 secreting melanoma cell lines." (PMID 25051363, 2014). "This study examined the roles of THBS1, a gene which is highly expressed in mesenchymal-like but not or at lower levels in epithelial-like melanoma cell lines." (PMID 25051363, 2014). "Using that approach, the proteomic comparison of melanoma-derived plasma exosomes with remaining non-melanoma plasma exosomes showed an increase in signaling and immune regulating proteins including LDHA, NOTCH2 and thrombospondin-1 among others." (PMID 36704194, 2022).
glioma (42 papers, 2009 to 2026). A benign or malignant brain and spinal cord tumor that arises from glial cells (astrocytes, oligodendrocytes, ependymal cells). "Upregulation of Thbs1 has been shown to be increased in glioma of higher grade and has been associated with poor prognosis." (PMID 36717781, 2023). "In this study, global expression analysis revealed THBS1 to be upregulated in high-grade gliomas and to be associated with a poor prognosis." (PMID 30850588, 2019). "Among the identified genes, thrombospondin-1 (THBS1) emerged as a significant player in glioma pathology." (PMID 41432874, 2025). "This study revealed that miR-338-3p prevented glioma tumorigenesis by targeting THBS1 to inhibit the activation of the PI3K/Akt pathway." (PMID 38267974, 2024). "Apatinib targets platelet-responsive protein 1 (THBS1) in glioma cells, thereby inhibiting glioma cell malignancy through its interaction with MYH9." (PMID 39149512, 2024). "A previous study showed that THBS1 knockdown inhibited glioma tumorigenesis by regulating the focal adhesion kinase/Akt signaling pathway." (PMID 38267974, 2024). "In gliomas, miR-338-3p expression was negatively correlated with THBS1 expression, as determined by Spearman’s test (R2 = 0.7068; P < 0.0001)." (PMID 38267974, 2024). "Here, we demonstrated, for the first time, the targeting role of miR-338-3p on THBS1, showing that miR-338-3p exerted its antitumor effect on glioma by targeting THBS1." (PMID 38267974, 2024). "We further investigated the function of THBS1 and its regulatory relationship with miR-338-3p in gliomas." (PMID 38267974, 2024). "Gliomas exhibiting high functional connectivity express thrombospondin-1, which is an astrocyte-derived synaptogenesis factor." (PMID 39258226, 2024). "The present study revealed that THBS1 overexpression enhanced the proliferation and migration of glioma cells, suggesting an oncogenic role of THBS1 in glioma." (PMID 38267974, 2024). "Wound-healing and cell-counting-kit-8 experiments were performed to analyze how THBS1 and miR-338-3p affect the ability of glioma cells to migrate and proliferate." (PMID 38267974, 2024). "Our present study makes a new attempt to reveal how the miR-338-3p/PI3K/Akt/THBS1 axis functions in gliomas." (PMID 38267974, 2024). "The miR-338-3p/PI3K/Akt/THBS1 regulatory axis can modulate the progression of glioma cell proliferation and migration; thus, it can be considered a therapeutic biomarker." (PMID 38267974, 2024). "The details of the relative contribution of thrombospondin-1 from glioma cells and resident astrocytes to the enhanced functional network in glioma tissue remain to be elucidated at the cellular level." (PMID 39258226, 2024). "THBS1 overexpression promoted glioma cell migration and proliferation by increasing PI3K/Akt phosphorylation." (PMID 38267974, 2024). "The interactions between syndecans and thrombospondin-1 secreted by malignant glioma cells is a mechanism that increases the motility of glioma cells." (PMID 39770078, 2024). "Transfection with THBS1-OE significantly promoted the proliferation and migration of glioma cells (P < 0.001)." (PMID 38267974, 2024). "It has been suggested that the overexpression of Syndecan-1 in the glioma microenvironment induces tumor invasion through the upregulation of thrombospondin-1." (PMID 36980765, 2023). "The WT-1 protein is found secreted in glioma-derived EVs and downregulates thrombospondin-1 (Thbs1) in microglia, subsequently promoting angiogenesis which is vital in glioma progression." (PMID 36467419, 2022). "Compared with THBS1 overexpression (THBS1-OE) plus apatinb, apatinib inhibited glioma cell growth and progression." (PMID 34635636, 2021). "qPCR and western blotting revealed that THBS1 mRNA and THBS1 protein expression in glioma cells treated with apatinib was lower compared with the control group." (PMID 34635636, 2021).